RETN (resistin)
Diseases named in the same sentence as RETN in open-access papers (continued):
Sharing a sentence is not in itself a finding about the gene and the disease.
myocardial infarction (23 papers, 2008 to 2026). Gross necrosis of the myocardium, as a result of interruption of the blood supply to the area, as in coronary thrombosis. "It has been established that the risk of acute myocardial infarction (AMI) is twice as high in individuals with elevated serum resistin levels compared to those with normal levels." (PMID 40283140, 2025). "Patients with unstable angina and acute myocardial infarction (STEMI or NSTEMI) have elevated serum levels of resistin, suggesting a possible role as a diagnostic biomarker for acute coronary events." (PMID 30405857, 2018). "Intriguingly, we found a number of novel CS/CPB–induced genes such as PTX3, Toll-like receptors and resistin that were only recently linked to cardiac pathology, in particular myocardial infarction." (PMID 21048961, 2010). "Moreover, serum resistin levels were found to be elevated in patients with acute myocardial infarction (AMI) and identified as a risk factor for major adverse cardiovascular events (MACEs) in this group." (PMID 40283140, 2025). "Plasma levels of resistin in humans were either increased or unchanged after MI and high plasma levels are correlated with a higher risk for myocardial infarction." (PMID 36388122, 2022). "Beyond CRP, both IL-1ra and resistin exhibit specific temporal patterns during acute myocardial infarction." (PMID 41226718, 2025). "We also found that the levels of resistin in stable angina and in acute myocardial infarction were correlated with markers of inflammation and are predictive of AMI." (PMID 34745775, 2021). "The aim of this study is to evaluate the changes in the inflammatory mediator’s serum amyloid A (SAA), adiponectin, and resistin in the serum of patients with stable angina and acute myocardial infarction." (PMID 34745775, 2021). "In our study, we found that the serum resistin level was significantly higher (P-value=0.0) in the stable angina (8.368 ± 1.633 ng/ml) and acute myocardial infarction (13.606 ± 2.067 ng/ml) groups (P-value=0.0) than the control group (2.4272±1.25210 ng/ml)." (PMID 34745775, 2021). "In this context, high plasma resistin levels were found to predict mortality in patients with acute myocardial infarction and to worsen cardiac ischemia-reperfusion injury via impaired contractile recovery during reperfusion." (PMID 21048961, 2010). "Consistently, among patients with CAD, epicardial adipose tissue mRNA expression of resistin was found to be upregulated only in those with a history of myocardial infarction or those with acute coronary syndrome, implying the possible existence of the confounding effect of LV dysfunction." (PMID 36964443, 2023). "Several studies show an impact of resistin on cardiac metabolism and function in the context of cardiac hypertrophy, while its role after myocardial infarction is unclear." (PMID 36388122, 2022). "Also in the Ibrahim AE study, the resistin level was found higher in acute myocardial infarction patients than in a healthy normal group." (PMID 34745775, 2021). "The aim of this study is to evaluate the changes in the inflammatory mediator’s SAA, adiponectin, and resistin in the serum of patients with stable angina and acute myocardial infarction and correlate it with troponin-T and creatine kinase-myocardial band (CK-MB)." (PMID 34745775, 2021). "Furthermore, resistin was found to be an independent predictor of the main adverse cardiovascular events, including cardiovascular death, myocardial infarction, and restenosis in patients after transcutaneous transluminal coronary angioplasty." (PMID 32121175, 2020). "Moreover significant positive correlation of resistin was observed with TLC in hypertensive patients of myocardial infarction." (PMID 31258568, 2019). "Moreover, resistin levels in stable angina when compared to the AMI showed a significant difference between them (p-value = 0.0) while adiponectin was significantly lower in the acute myocardial infarction group." (PMID 34745775, 2021).
myocardial infarction (continued). "Several other studies reported high levels of resistin in patients with established CVD, including myocardial infarction, recurrent ischemic events, and overall with CVD complications." (PMID 34496965, 2021). "To date, only few studies show that resistin levels are correlated with cardiovascular death in patients with documented IHD, i.e. unstable angina and myocardial infarction." (PMID 30832662, 2019). "Significantly positive correlation of resistin was observed with TLC only in hypertensive patients of myocardial infarction (r = 0.459, n = 20, p = 0.042) while in other study groups correlation between resistin and TLC as well as CRP was non-significant." (PMID 31258568, 2019). "Although serum resistin levels did not demonstrate a link with a risk of non-fatal myocardial infarction in CAD patients and did not reduce infarct size, the highest quartile of resistin concentrations were found as an independent predictor of an increased risk of HF development." (PMID 33240938, 2020).
Stroke (22 papers, 2009 to 2025). Sudden impairment of blood flow to a part of the brain due to occlusion or rupture of an artery to the brain. "Other non-routine markers like fibrinogen, E-selectin, interferon-γ-inducible-protein-10, resistin, and total adiponectin have also been linked with increased risk of stroke." (PMID 40949739, 2025). "In atherothrombotic stroke patients, increased resistin values were associated with increased disability and increased five-year mortality risk as an independent predictive factor." (PMID 34445740, 2021). "Another study confirmed the same observation, which additionally showed a further ethnic difference in stroke patients, with a significant association between resistin values and acute ischemic stroke in the Asian population, but not in the Caucasian population." (PMID 34445740, 2021). "Furthermore, genetic polymorphism of resistin adds an extra layer of complexity to this connection, as resistin genotype −420 (C > G) is a supplementary stroke risk factor in type 2 diabetic Japanese patients." (PMID 34445740, 2021). "However, a couple of studies have focused on specific groups, such as the Japanese, where high resistin values were found to be an independent risk factor for atherothrombotic stroke in the general population." (PMID 34445740, 2021). "Adiponectin, resistin and lipids have also been linked to increased stroke risk in people." (PMID 31865538, 2020). "However, altered blood lipids, increased plasma resistin and changes in adiponectin have been reported as risk factors for stroke." (PMID 31865538, 2020). "The relationship of resistin with the risk of stroke requires a further study." (PMID 30405857, 2018). "In both females and males, the G allele of the 420C/G of the resistin gene polymorphism appears to be associated with higher risk for cardiovascular events, cerebrovascular disease, and stroke: more severe stroke and higher in-hospital mortality in patients with acute ischemic stroke." (PMID 30405857, 2018). "Alterations in plasma adiponectin and resistin have both been implicated in stroke risk in patients, although adipokines more generally could affect stroke outcome by modulating the immune system, vasculature, and energy homeostasis." (PMID 28798136, 2017). "A recently published review paper from 104 articles also did not give a clear conclusion whether adiponectin, leptin, and resistin levels or the single-nucleotide polymorphisms of their encoding genes are independently associated with stroke risk." (PMID 29225622, 2017). "High resistin levels have been observed in patients with cardiovascular diseases, including stroke, which suggests its potential role in promoting the pro-inflammatory state associated with acute ischemic stroke." (PMID 39336454, 2024). "By promoting cardiac hypertrophy and remodeling, resistin contributes to reducing cardiac output, which, in turn, exacerbates low cerebral blood flow and increases the likelihood of adverse outcomes post-stroke." (PMID 39336454, 2024). "Several strengths of the study include its prospective nature, an adequate number of patients that enhances statistical significance, and is the first study to prove that resistin can predict in-hospital mortality after stroke." (PMID 39201031, 2024). "In a model of brain ischemia/reperfusion damage was found that resistin administration prior to the stroke induction, reduced infarct size and improved outcome, reducing cleaved levels of PARP-1 used as a marker of cellular apoptosis." (PMID 36745280, 2023). "Despite its role in inflammation, resistin appears to exert a neuroprotective effect in murine stroke models." (PMID 36745280, 2023). "Several studies aimed to investigate the incidence of stroke in patients with high serum resistin values." (PMID 36745280, 2023). "In women patients that had already developed an ischemic stroke, a higher resistin value was positively correlated with stroke severity using NIHSS score." (PMID 34445740, 2021).
Stroke (continued). "As a treatment option, resistin experimental studies on mice were performed, showing that resistin peak values are around 12 h from the stroke onset, reversing to basal values at 24 h." (PMID 34445740, 2021). "Changes in plasma adipokines and lipids in patients after stroke have been studied poorly, but a few studies report early increases in resistin and triglycerides." (PMID 31865538, 2020). "Adipokines such as resistin and adiponectin are released from adipose tissue and early changes in both are reported in mice after stroke, suggesting disturbances in metabolic status." (PMID 31865538, 2020). "Resistin concentrations were significantly increased after stroke in the adipose tissue and plasma, and adiponectin concentrations were increased in the plasma." (PMID 31865538, 2020). "In the epididymal adipose tissue in both naïve mice and post-stroke, obese ob/ob mice had significantly lower expression of both resistin and adiponectin compared with control mice." (PMID 28798136, 2017). "Stroke then resulted in a significant decrease in plasma concentrations of both resistin and adiponectin." (PMID 28798136, 2017). "Because both resistin and adiponectin are exclusively released by adipocytes in mice, this suggests that stroke can alter the release of adipokines from adipose tissue." (PMID 28798136, 2017). "Post-stroke plasma concentrations of resistin were significantly lower in both genotypes, and there was a significant effect of treatment (pre- versus post-stroke) on adiponectin concentrations." (PMID 28798136, 2017). "In a recent meta-analysis, resistin was associated with a higher risk of stroke but not with mid-term or long-term mortality, although this was the situation for other adipokines." (PMID 39336454, 2024). "Studies have shown that resistin levels rise after acute ischemic events, including stroke." (PMID 39201031, 2024). "Although resistin and leptin have been studied in relation to the risk of stroke and mortality in patients with AIS, our study is, to the best of our knowledge, the first to incorporate resistin into a validated predictive score for three-year mortality in AIS patients." (PMID 39336454, 2024). "However, we found that stroke resulted in a decrease in plasma resistin and adiponectin in both control and obese mice." (PMID 28798136, 2017). "However, studies are contradictory regarding the role of resistin in stroke." (PMID 39777314, 2024). "The CytoHubba plug-in of the Cytoscape was utilized to visualize the genes of stroke-related crucial module, and the top five genes were selected as hub genes using EcCentricity as the ranking method (MPO, MMP9, ITGA2B, ITGB3, and RETN)." (PMID 35557984, 2022). "Serum adiponectin, leptin, and resistin levels were determined by ELISA in 99 AIS patients and 59 stroke-free control group subjects." (PMID 29225622, 2017). "The multivariate analysis, however, showed that only high resistin values, large lesion volume, high NIHSS score, and IHD could be regarded as predictors of in-hospital mortality in patients with stroke." (PMID 39201031, 2024). "For example, stroke did not induce a significant increase in resistin in the adipose tissue in obese mice." (PMID 31865538, 2020). "Non-obese animals also had higher plasma concentrations of resistin and adiponectin after stroke." (PMID 31865538, 2020). "Indeed, accumulating evidence from human epidemiological studies indicates that an increased circulating level of resistin may be related to increased risks of many cardiovascular diseases, including CHD and stroke." (PMID 29848323, 2018). "Although the level of resistin is similar to our study, the OPERA cohort included an elderly population in general, not just those with stroke, and followed them for long periods of time (approximately six years)." (PMID 39201031, 2024).
colorectal cancer (21 papers, 2010 to 2025). A primary or metastatic malignant neoplasm that affects the colon or rectum. "TFF3, TFF1, SELE, AHCY, LCN2, CEACAM5, and RETN are consistently upregulated across a variety of datasets and analyzes, which supports their crucial roles in the underlying mechanisms of colorectal cancer progression." (PMID 39839775, 2024). "Association of resistin, leptin, adiponectin, and visfatin with the development of colorectal cancer." (PMID 39184804, 2024). "It is concluded that glucose metabolism status along with resistin should be considered in risk assessment for the development of precancerous colorectal lesions and colorectal carcinomas." (PMID 39184804, 2024). "We conducted a two-sample Mendelian randomization to estimate the association between genetically determined circulating resistin concentrations and risk of colorectal cancer (CRC)." (PMID 37599317, 2023). "Previous pooled analysis demonstrated increased resistin circulating levels to be associated with a higher risk for colorectal cancer." (PMID 35073877, 2022). "In conclusion, our study suggests that circulating resistin levels in patients with CRC are significantly higher than those in healthy controls, increasing the current understanding of the association between resistin levels and risk of colorectal cancer." (PMID 27642602, 2016). "Neither separate analysis of studies matching for BMI yielded significant associations of resistin levels and colorectal cancer risk." (PMID 27642602, 2016). "Our meta-analysis suggests that increased circulating resistin levels are associated with greater risk of colorectal cancer." (PMID 27642602, 2016). "Additionally, specific polymorphisms in the resistin gene have been linked to colorectal cancer risk, though findings are inconsistent across different populations." (PMID 39184804, 2024). "However, positive association was observed between resistin levels and risk of colorectal cancer in serum samples, studies with ELISA method, low quality studies, studies of Asian origin, and case-control design, indicating the possible origin of heterogeneity." (PMID 27642602, 2016). "Elevated resistin levels have been observed in colorectal cancer patients, correlating with advanced tumor stages and poorer prognosis." (PMID 39184804, 2024). "RETN binds to toll-like receptor 4 (TLR4) on the surface of colorectal cancer cells, switching on ERK signaling." (PMID 39839775, 2024). "In case-control studies, higher resistin levels have been found in colorectal cancer (CRC) patients compared to healthy individuals." (PMID 36428592, 2022). "Our study has identified high levels of resistin expression in colorectal cancer tissue and a positive correlation between this expression and disease progression in patients." (PMID 32420377, 2020). "The discrepancy highlights the need for well-designed prospective studies on resistin and colorectal cancer." (PMID 27642602, 2016). "A high level of serum resistin has recently been found in patients with a number of cancers, including colorectal cancer (CRC)." (PMID 26690142, 2015). "Mounting evidence indicates that serum resistin is proportionally related to cancer development, including: breast, gastric, and colorectal cancers as well as lymphoma." (PMID 24555415, 2014). "In this study, the colorectal cancer cell line ability was assessed to express resistin mRNA and protein." (PMID 24551805, 2013). "In one study, increased resistin and low adiponectin serum levels negatively correlated with the stage were reported in colorectal cancer." (PMID 21254741, 2010). "Targeting resistin and its pathways may offer novel therapeutic strategies for colorectal cancer, but further research is essential to understand its mechanisms and clinical applications fully." (PMID 39184804, 2024). "Since inflammation predisposes colorectal cancer (CRC) and promotes its development, resistin has been proposed as a molecule that may be linked to cancer development." (PMID 37599317, 2023).